KIF23 (kinesin family member 23)
Diseases named in the same sentence as KIF23 in open-access papers (continued):
Sharing a sentence is not in itself a finding about the gene and the disease.
endometrial carcinoma (3 papers, 2018 to 2024). A malignant tumor arising from the epithelium that lines the cavity of the uterine body. "Immunohistochemistry, Western blotting, and PCR were used to examine the expression of KIF23 and its associated pathway factors in endometrial cancer tissue (specifically Ishikawa and SNGM cells, respectively)." (PMID 38514510, 2024). "Furthermore, increased KIF23 expression in endometrial cancer patients is associated with a poor prognosis." (PMID 38514510, 2024). "To confirm these findings, we evaluated the expression levels of KIF23 protein in endometrial carcinoma tissues and normal endometrium obtained from the First Affiliated Hospital of Jinzhou Medical University." (PMID 38514510, 2024). "Our research has shown that specifically targeting KIF23 with shRNA can effectively inhibit endometrial cancer cell growth both in vitro and in vivo." (PMID 38514510, 2024). "Immunohistochemistry analysis showed variations in the expression levels of KIF23 between endometrial cancer tissue and normal endometrium tissue." (PMID 38514510, 2024). "Immunohistochemical analysis showed that tumor tissues of endometrial cancer expressed higher levels of KIF23 compared to normal endometrium." (PMID 38514510, 2024). "Our research aims to understand the functional effectiveness of KIF23 as a therapeutic agent for endometrial cancer, thereby laying the groundwork for its potential application in EC therapy (Additional fle 1)." (PMID 38514510, 2024). "To summarize, our findings suggest that KIF23 plays a crucial role in the development of endometrial cancer." (PMID 38514510, 2024). "Mechanistically, our study provides evidence that KIF23 promotes endometrial cancer cell proliferation by activating the ERK and AKT/PI3K pathways, while simultaneously inhibiting programmed cell death in endometrial cancer." (PMID 38514510, 2024). "CCK-8 analysis demonstrated that KIF23 knockdown significantly inhibited endometrial cancer cell proliferation." (PMID 38514510, 2024). "Subsequently, we developed a nude mouse model for the heterogeneous transplantation of endometrial cancer to validate the inhibitory effect of KIF23 on endometrial cancer development in vivo." (PMID 38514510, 2024). "This emphasizes the importance of further investigating the role of KIF23 in endometrial cancer." (PMID 38514510, 2024). "Additionally, knocking out KIF23 inhibits endometrial cancer cell proliferation and migration while promoting cell death." (PMID 38514510, 2024). "The significant upregulation of KIF23 in endometrial cancer compared to normal endometrial tissue strongly suggests that KIF23 could be a promising therapeutic target for effective endometrial cancer treatment." (PMID 38514510, 2024). "Based on these findings, KIF23 may play a role in the poor prognosis of endometrial cancer patients." (PMID 38514510, 2024). "Our study provides evidence to support the inhibition of endometrial cancer by KIF23 knockdown." (PMID 38514510, 2024). "Hence, gene therapy targeting KIF23 shows promise as an advanced strategy for the treatment of endometrial cancer." (PMID 38514510, 2024). "We propose that KIF23 may serve as a potential prognostic marker for endometrial cancer." (PMID 38514510, 2024). "We silenced KIF23 in Ishikawa and SNGM endometrial cancer cell lines to investigate its effects on tumor growth." (PMID 38514510, 2024). "To investigate the relationship between KIF23 and the development of endometrial cancer, we analyzed KIF23 mRNA expression using the GEPIA database and corresponding endometrial cancer dataset." (PMID 38514510, 2024). "Survival analysis showed that the higher the expression levels of lncRNAs C2orf48, PSAT1, KIF23, CCNE1, CDC25A and CBX2 in patients with endometrial cancer, the poorer the prognosis." (PMID 30581678, 2018).
glioblastoma (3 papers, 2013 to 2025). The most malignant astrocytic tumor (WHO grade IV). "Particularly, RRM2 and KIF23, with the highest node degrees of 22, were closely associated with poorer overall survival rates, underscoring their potentially critical roles in glioblastoma oncogenesis." (PMID 39248068, 2025). "Moreover, alterations in RRM2 and KIF23 were associated with diminished disease-free survival rates for glioblastoma patients, as illustrated in Fig.." (PMID 39248068, 2025). "The analysis indicated that glioblastoma patients exhibiting genomic alterations in PCNA clamp-associated factor (PCLAF), RRM2, nucleolar and spindle-associated protein 1 (NUSAP1), and KIF23 displayed reduced overall survival rates, as shown in Fig.." (PMID 39248068, 2025). "We assayed cell cycle-dependent binding of DREAM and MMB complexes to the KIF23 promoter in vivo performing chromatin immunoprecipitations (ChIPs) in serum-starved (0 h) and restimulated (22 h) human glioblastoma T98G cells." (PMID 23650552, 2013). "In future studies, we may combine gene expression levels of RRM2 and KIF23 and cell biological behavior analysis to further explore the oncogenesis of glioblastoma." (PMID 39248068, 2025). "For grade 4 glioblastoma brain cancer, CCNB1 was indicated as a part of hub genes (with CDC6, KIF23, and KIF20A) and its expression correlated with prognosis, suggesting it as a potential biomarker for diagnosis and as a target for treatment." (PMID 39409884, 2024).
malignant pleural mesothelioma (3 papers, 2019 to 2021). A malignant neoplasm that arises from mesothelial cells in the pleura and shows a diffuse growth pattern. "A high level of KIF23 expression was observed in most malignant pleural mesothelioma cases and is associated with poor survival." (PMID 30872592, 2019).
microcephaly (3 papers, 2024 to 2025). A congenital or acquired developmental disorder in which the circumference of the head is smaller than normal for the person's age and sex. "While mutations in the kinesin-like motor protein KIF23 gene have been recently linked to microcephaly in humans, the underlying mechanisms remain elusive." (PMID 39632980, 2024). "Since mutations of the human KIF23 gene are reported in cases of microcephaly, we explored the role of KIF23." (PMID 39632980, 2024). "Next, we asked about potential means of a mutation related to microcephaly by rescuing Kif23-deficient condition." (PMID 39632980, 2024). "Similarly, genes such as PRKDC, ALPL, and KIF23, which are linked to microcephaly (scores ranging from 0.40 to 0.45), are involved in key cellular functions such as DNA repair, motor protein activity, and cytokinesis." (PMID 41033462, 2025). "Notably, recent genetic studies in humans have identified mutations in human KIF23 gene associated with microcephaly." (PMID 39632980, 2024). "This study uncovers a role of KIF23 in maintaining neural stem and progenitor cells (NSPCs) during cortical development, offering insights into the mechanisms of microcephaly pathogenesis." (PMID 39632980, 2024). "Our findings unveil a previously unexplored role of KIF23 in neural stem and progenitor cell maintenance via regulating spindle orientation and apical structure in addition to cytokinesis, shedding light on microcephaly pathogenesis." (PMID 39632980, 2024). "We further demonstrate that the phenotypes induced by Kif23 knockdown are rescued by introducing wild-type human KIF23, but not by a microcephaly-associated variant." (PMID 39632980, 2024). "Thus, our findings offer novel insights into how KIF23 dysfunction in humans may contribute to microcephaly by uncovering previously unexplored cellular and molecular mechanisms of Kif23 in NSPC maintenance." (PMID 39632980, 2024). "Notably, the introduction of human KIF23 bearing a mutation associated with microcephaly failed to rescue the defects induced by Kif23-KD in the developing cortex." (PMID 39632980, 2024). "Considering that this is a missense mutation, and that severe microcephaly has only been identified in individuals who are homozygous for this mutation, it is plausible that this missense mutation might partially impair KIF23 function rather than completely abolishing it." (PMID 39632980, 2024).
adrenocortical carcinoma (2 papers, 2021 to 2023). "In addition, we observed that in certain tumors, such as adrenocortical carcinoma and mesothelioma, ERFE was positively co-expressed with the NCAPH and KIF23 genes, which facilitate the separation of chromosomes and cytokinesis during mitosis, thereby promoting tumor cell proliferation." (PMID 36675239, 2023).
esophageal cancer (2 papers, 2020 to 2023). A primary or metastatic malignant neoplasm involving the esophagus. "We analyzed the correlations in TIMER between KIF23 and marker genes of different immune cells, including CD8+ T cells, T cells(general), B cells, monocytes, TAMs, M1 macrophages, M2 macrophages, neutrophils, NK cells, and DCs in GC, using esophageal carcinoma (ESCA) as the control." (PMID 37483517, 2023).
Fanconi anemia (2 papers, 2023). Fanconi anemia (FA) is a hereditary DNA repair disorder characterized by progressive pancytopenia with bone marrow failure, variable congenital malformations and predisposition to develop hematological or solid tumors. "The results of KEGG pathway analysis showed that the functions of KIF23 and its neighboring genes were mainly enriched in the cell cycle, DNA replication, Fanconi anemia pathway and homologous recombination." (PMID 37483517, 2023).
head and neck squamous cell carcinoma (2 papers, 2025). A squamous cell carcinoma that arises from any of the following anatomic sites: lip and oral cavity, nasal cavity, paranasal sinuses, pharynx, larynx, and salivary glands. "Furthermore, the interaction between SHCBP1 and KIF23 plays functional roles in modulating the cell cycle and cisplatin resistance in head and neck squamous cell carcinoma." (PMID 40789837, 2025). "In head and neck squamous cell carcinoma (HNSCC), SHCBP1 cooperates with KIF23 to regulate cell-cycle progression through several oncogenic signaling pathways." (PMID 40799237, 2025).
ovarian tumor (2 papers, 2020 to 2022). "As a member of KIF family, KIF23 promotes ovarian tumor proliferation, cell cycle progression and is closely related to metastasis." (PMID 35478956, 2022). "KIF23 has been suggested to promote cell proliferation and migration, and KIF23-expression to be coupled to poor OS prognosis in ovarian tumors." (PMID 32133296, 2020).
sarcoma (2 papers, 2017 to 2025). A usually aggressive malignant neoplasm of the soft tissue or bone. "Indeed, we observed by immunofluorescence that a number of mitotic proteins, such as KIF11, KIF23 and PLK1 were overexpressed in interphase in sarcoma cell lines (data not shown)." (PMID 28035071, 2017).
astrocytoma (1 paper, 2019). "Additionally, we observed that the mRNA levels of KIF4A, KIF9, KIF18A, and KIF23 were elevated in LGG patients with a higher histological grade and astrocytoma histologic type than in those with a lower histological grade and histologic type, including oligoastrocytoma and oligodendroglioma." (PMID 30872592, 2019).
breast invasive carcinoma (1 paper, 2020). "By comparison with the top 200 up-regulated genes in breast invasive carcinoma (BRCA) from GEPIA database, only three genes (KIF23, PRC1, CDCA3) were screened for further research." (PMID 32944002, 2020).
carcinoma in situ (1 paper, 2018). "In the transition of squamous severe dysplasia to carcinoma in situ, the genes UBET2 PIH1D2, KIF23 showed a change in their entropy." (PMID 33265245, 2018).
colon cancer (1 paper, 2022). "A recent paper showed that KIF23 and RACGAP1, as part of the midbody remnant formed during cytokinesis, were part of a subpopulation of EVs in colon cancer that could promote an invasive phenotype in fibroblasts." (PMID 35918030, 2022).
cyst (1 paper, 2025). A sac-like closed membranous structure that may be empty or contain fluid or amorphous material. "An example of such a cyst fortuitously labeled with EdU and ring canals (via Kif23, a kinesin family member and component of the centralspindlin complex) as an 8-cell cyst now shows two closely associated but separate 6-cell and 2-cell groups with no ring canal between them." (PMID 41213017, 2025).
gastric adenocarcinoma (1 paper, 2023). "Furthermore, the expression of KIF23 in gastric adenocarcinoma tissue may be a biomarker for diagnosis and efficacy of immunotherapy in patients." (PMID 37483517, 2023).
hereditary spherocytosis (1 paper, 2025). Hereditary spherocytosis is a congenital hemolytic anemia with a wide clinical spectrum (from symptom-free carriers to severe hemolysis) characterized by anemia, variable jaundice, splenomegaly and cholelithiasis. "WES confirmed a KIF23 mutation, reinforcing its diagnostic value in distinguishing CDA III from other hemolytic anemias, including hereditary spherocytosis, pyruvate kinase deficiency, or others, which can share overlapping morphologic bone marrow results." (PMID 40927401, 2025).
liposarcoma (1 paper, 2007). A usually painless malignant tumor that arises from adipose tissue. "Genes highly expressed in the dedifferentiated/pleomorphic liposarcomas included cell-cycle genes like CCNA2, CCNB2, CDC2, KIFC1, KIF23 and PTTG1, motility genes like AMFR, ANXA1, CKB, CNN2 and FN1 and homeostasis-related genes." (PMID 17359542, 2007).
lymph node metastasis (1 paper, 2022). "Moreover, the expression of KIF23 in patients without lymph node metastasis was significantly lower than that in patients with lymph node metastasis." (PMID 35524313, 2022).
malignant glioma (1 paper, 2021). A grade III or grade IV glioma arising from the central nervous system. "However, the mechanism underlying KIF23 overexpression in malignant glioma remains to be elucidated." (PMID 34017355, 2021).
papillary thyroid carcinoma (1 paper, 2025). "This study aims to explore the function of KIF23 and its underlying regulatory mechanisms in the progression of papillary thyroid carcinoma (PTC)." (PMID 41138746, 2025).
Primary microcephaly (1 paper, 2020). Head circumference below 2 standard deviations below the mean for age and gender at birth. "Genes associated with primary microcephaly were often differentially expressed during development, with highest expression during the early embryonic and fetal periods (ASPM, WDR62, MCPH1, STIL, KIF23 and TTI1)." (PMID 32182809, 2020).
pulmonary arterial hypertension (1 paper, 2020). Pulmonary arterial hypertension (PAH) is a group of diseases characterized by mean pulmonary artery pressure >20 mmHg and elevated pulmonary arterial resistance leading to right heart failure. "Among them, KIF23 and ARHGAP11A were down-regulated in pulmonary arterial hypertension patients, which might have a protective role in PAH." (PMID 32886110, 2020).
Right ventricular hypertrophy (1 paper, 2022). In this case the right ventricle is more muscular than normal, causing a characteristic boot-shaped (coeur-en-sabot) appearance as seen on anterior- posterior chest x-rays. "Compared with MCT-induced IPAH rats, KIF23 knockdown significantly reduced the pulmonary arterial pressure, right ventricular hypertrophy, pulmonary vascular resistance, end-systolic pressure, and pulmonary vascular remodeling." (PMID 35457254, 2022). "Knockdown of KIF23 in PASMCs could significantly suppress the PASMCs’ pyroptosis and proliferation and then alleviate the increase in pulmonary arterial pressure, right ventricular hypertrophy, and pulmonary vascular resistance in IPAH." (PMID 35457254, 2022).
thyroid carcinoma (1 paper, 2024). "In addition, THCA database showed that KIF23 was upregulated in cancer samples compared with the normal samples in thyroid carcinoma." (PMID 38360598, 2024).
thyroid-associated ophthalmopathy (1 paper, 2024). "A similar study shows that KIF23 is enriched in cell cycle programs in patients with thyroid-associated ophthalmopathy." (PMID 38360598, 2024).
vitiligo (1 paper, 2021). Generalized well circumscribed patches of leukoderma that are generally distributed over symmetric body locations and is due to autoimmune destruction of melanocytes. "The hub genes of vitiligo melanocytes include CDK1, HSP90AA1, AKT1, BCL2L1, HDAC2, HELLS, and KIF23." (PMID 33790887, 2021).